MCL1 (MCL1 apoptosis regulator, BCL2 family member)
Diseases named in the same sentence as MCL1 in open-access papers (continued):
Sharing a sentence is not in itself a finding about the gene and the disease.
non-Hodgkin lymphoma (9 papers, 2012 to 2024). Distinct from Hodgkin lymphoma both morphologically and biologically, non-Hodgkin lymphoma (NHL) is characterized by the absence of Reed-Sternberg cells, can occur at any age, and usually presents as a localized or generalized lymphadenopathy associated with fever and weight loss. "MCL-1 indicates Burkitt lymphomasubline exhibit enhance survival exposure to serum deprivation.MCL-1 related to a vascular endothelial growth factor is associatedwith pore outcome in non-Hodgkin's lymphoma." (PMID 31285648, 2019). "Long-term ABT199 treatment of non-Hodgkin lymphoma cells resulted in upregulated levels of anti-apoptotic proteins MCL-1 and BCL-XL that sequestered BIM." (PMID 27056887, 2016). "In non-Hodgkin lymphoma, MCL1 expression was significantly lower in patients in complete remission than with progressive disease." (PMID 23482333, 2012). "When PV was used in combination with venetoclax and anti-CD20 antibodies obinutuzumab or rituximab, the targeted MCL-1 antagonistic effect led to tumor regression in preclinical non-Hodgkin lymphoma (NHL) models." (PMID 38519953, 2024). "A somatically acquired increase in MCL-1 copy number has been documented in a variety of non-hematopoietic malignancies, but only in a limited number of non-Hodgkin lymphomas." (PMID 30671383, 2018). "Omacetaxine, previously identified as homoharringtonine (HHT), is a natural alkaloid originating from Cephalotoxus fortunei with an anticancer activity that operates synergistically with different drugs in non-Hodgkin lymphoma (NHL) via NOXA and MCL-1-dependent systems." (PMID 35406692, 2022). "The first synthetic BH-3 mimetic was ABT-737, a small-molecule that binds with high affinity to BCL-2, BCL-X, and BCL-W, but not MCL-1 or A1/BFL-1, and was shown to efficiently induce apoptosis at sub-micromolar concentrations in a variety of non-Hodgkin lymphoma cell lines and in primary CLL cells." (PMID 30671383, 2018).
esophageal cancer (8 papers, 2014 to 2025). A primary or metastatic malignant neoplasm involving the esophagus. "They noticed that elevated USP20 expression is associated with higher levels of MCL1 protein in esophageal cancer cell lines." (PMID 39931465, 2025). "CircRNA-DOPEY2 was found to enhance chemosensitivity of esophageal cancer cells by inhibiting cytoplasmic polyadenylation element binding protein 4 (CPEB4)-mediated translation of MCL1 (encoding myeloid cell leukemia 1)." (PMID 36609391, 2023). "Mcl-1 expression is critical to maintaining minority MOMP in esophageal cancer models, but this function has yet to be highlighted in other cancers." (PMID 38622136, 2024). "Because Mcl-1 is an important antiapoptotic protein in the cell death pathway, targeting CDK to decrease Mcl-1 expression or enhance Mcl-1 degradation is a rational option for treatment of various cancers including esophageal cancer." (PMID 34621175, 2021). "The Mcl-1 protein levels among these esophageal carcinoma cell lines were similar." (PMID 24529193, 2014). "The distinctive patterns for constitutively activated NF-κB subtypes in different ESCC cell lines suggested that NF-κB subunits might play a specific role in regulating Mcl-1 in different esophageal carcinoma cell lines." (PMID 24529193, 2014). "Expression of Mcl-1 has been shown in human esophageal carcinoma cell lines CE81T/VGH and KYSE450." (PMID 24529193, 2014). "In this study, flavopiridol drastically decreased expression of the antiapoptotic protein Mcl-1 in OE19 and OE33 esophageal cancer cells." (PMID 34621175, 2021). "NF-κB dependent upregulation of Mcl-1 confers chemo/radiotherapy resistance in NSCLC and esophageal carcinoma." (PMID 32276600, 2020). "Four human esophageal carcinoma cell lines, including TE-1, Eca109, KYSE150 and KYSE510 revealed increased levels of Mcl-1 protein compare with an immortal non-tumorigenic keratinocyte HaCaT cell line, which was used as a normal control for Mcl-1 expression." (PMID 24529193, 2014).
laryngeal carcinoma (8 papers, 2015 to 2025). Carcinoma that arises from the laryngeal epithelium. "The present study also provides in vivo evidence that ERp57 expression was tightly associated with the expression of phosphorylated STAT3 or Mcl-1 in laryngeal cancer tissues." (PMID 25605256, 2015). "The decreased expression of USP9X subsequently reduced Mcl-1 expression and increased Bax expression, which may be the cause of apoptosis in laryngeal cancer cells." (PMID 37057289, 2023). "In addition, we showed that ERp57 expression was tightly associated with phosphorylated STAT3 and Mcl-1 expression in laryngeal cancer tissues." (PMID 25605256, 2015). "Overexpression of miR-1469, on the other hand, was found to inhibit expression of myeloid cell leukemia-1 (MCL1) and consequently promote apoptosis in laryngeal cancer cells." (PMID 34469478, 2021). "The miR-363 is able to suppress myeloid cell leukemia 1 (Mcl-1), which leads to reduced proliferation and invasion of laryngeal cancer cells." (PMID 32503307, 2020). "Next, we examined whether Mcl-1 downregulation with siRNA modulates the radiation sensitivity of radioresistant laryngeal cancer cells." (PMID 25605256, 2015). "Moreover, PDIA3 modulates radioresistance of laryngeal cancer cells by directly activating STAT3 and, in turn, triggers increased Mcl-1 expression, thereby contributing to tumor radioresistance of laryngeal cancer cells and poor outcomes in patients with laryngeal cancer in response to radiotherapy." (PMID 29228584, 2017). "Inhibition of STAT3 activity with a chemical inhibitor or siRNA-mediated depletion of Mcl-1 sensitized radioresistant cells to irradiation, suggesting that the ERp57-STAT3-Mcl-1 axis regulates radioresistance of laryngeal cancer cells." (PMID 25605256, 2015). "We demonstrated that ERp57 modulated radioresistance of laryngeal cancer cells by directly activating STAT3 and, in turn, triggered increased Mcl-1 expression, thereby contributing to tumor radioresistance of laryngeal cancer cells." (PMID 25605256, 2015). "Furthermore, we observed a positive correlation between ERp57 and phosphorylated STAT3 or Mcl-1 and in vivo interactions between ERp57 and STAT3 in human laryngeal cancer." (PMID 25605256, 2015).
medulloblastoma (8 papers, 2019 to 2025). A malignant, invasive embryonal neoplasm arising from the cerebellum. "Collectively, our study identifies that BCL-XL and MCL-1 are the key anti-apoptotic proteins in medulloblastoma, which mediate distinct protective roles." (PMID 37898609, 2023). "The MCL-1 inhibitor A-1210477 is shown to synergise with the Hedgehog pathway inhibitor GANT61 in a subset of medulloblastoma cell lines." (PMID 35568716, 2022). "In accordance with the reduction of MCL-1 levels by dinaciclib in HD-MB03 and ONS76 cells, we investigated if MCL-1 down-regulation was in part accountable for dinaciclib-inhibitory effects in medulloblastoma." (PMID 33686114, 2021). "To further elucidate simvastatin-induced cell death in medulloblastoma cells, we investigated the expression of anti- and pro-apoptotic proteins in the Bcl-2 family [Mcl-1, Bcl-xl, Bcl-2 (anti-apoptotic) and Bax (pro-apoptotic) at 24 h, 48 h, and 72 h]." (PMID 31319483, 2019). "Thus, FBXW7 may modulate apoptosis by promoting MCL-1 degradation in medulloblastoma." (PMID 33494392, 2021). "Additional targets of FBXW7, including AURORA A MCL-1, and Cyclin E, were also downregulated in response to PCM-075 in MB cells, implying FBXW7 is an upstream regulator of c-MYC in medulloblastoma." (PMID 33494392, 2021). "MiR-193a mediated decrease in the expression levels of known targets CCND1, MCL1, and the novel target MAX in the medulloblastoma cells was validated by the western blot analysis." (PMID 32410663, 2020). "Furthermore, miR-193a also brought about a substantial increase in the radiation sensitivity of the medulloblastoma cells, which is likely to be the result of the downregulation of DNA replication, DNA repair machinery, and decrease in the levels of its anti-apoptotic target MCL1." (PMID 32410663, 2020). "In MYC−driven medulloblastoma, inhibition of PLK1 stabilizes FBXW7, underscoring its tumor‐suppressive function, while blocking ELK1−mediated transcription activates FBXW7 and suppresses MCL1, leading to cytotoxicity." (PMID 40370434, 2025). "Here, we showed that simvastatin decreased Mcl-1 expression in Daoy and D341, without being changed in D283 medulloblastoma cells." (PMID 31319483, 2019). "Despite the observed BCL-XL dependence of medulloblastoma, we found that WEHI-539 treatment alone failed to effectively induce apoptosis, but that co-inhibition of MCL-1 successfully resulted in cell death." (PMID 37898609, 2023).
Obesity (8 papers, 2018 to 2024). Accumulation of substantial excess body fat. "Obesity and IL-6 increase the incidence of hepatocellular carcinoma development through Mcl-1 stabilization and apoptosis suppression." (PMID 35937685, 2022). "As a result, obesity suppresses hepatocyte apoptosis through Mcl-1 stabilization and promotes liver carcinogenesis." (PMID 30176860, 2018). "Moreover, STAT3, MCL1, PMAIP1, SOD2, FOXO3, FOS, FKBP5 may play an essential role in the genesis and growth of obesity and might serve as a possible therapeutic target." (PMID 34712134, 2021). "In obesity, the expression of HUWE1 was found to be suppressed, leading to stabilization of Mcl-1 independent of IL-6Ra signaling, which contributed to liver carcinogenesis." (PMID 35937685, 2022). "On the other hand, the anti-apoptotic Mcl-1 levels were decreased, while the expression of TG2 was not altered in the gWAT adipocytes during diet-induced obesity." (PMID 31165747, 2019).
anaplastic large cell lymphoma (7 papers, 2014 to 2022). Anaplastic large cell lymphoma (ALCL) is a rare and aggressive peripheral T-cell non-Hodgkin lymphoma, belonging to the group of CD30-positive lymphoproliferative disorders, which affects lymph nodes and extranodal sites. "Inhibition of mTOR with rapamycin- or mTOR-specific small interfering RNA downregulated Bcl-2 and Mcl-1 in anaplastic large-cell lymphoma cells." (PMID 24647338, 2014). "RNA-seq analysis of the LL-100 panel showed that cell lines derived from two rare lymphomas, anaplastic large cell lymphoma (ALCL) and from primary effusion lymphoma (PEL) stood out by high expression of MCL1." (PMID 35058488, 2022). "Anaplastic large cell lymphoma (ALCL) and primary effusion lymphoma (PEL), 2/22 entities covered by this panel, stood out by high expression of MCL1 and low expression of BCL2." (PMID 35058488, 2022).
lung squamous cell carcinoma (7 papers, 2013 to 2025). "Dual inhibition of BCL-XL and MCL-1 is required to induce tumor regression in lung squamous cell carcinomas sensitive to FGFR inhibition." (PMID 34351305, 2021). "Additionally, Mcl-1 expression in lung ADC was evidently higher than that of in lung squamous cell carcinoma (SCC)." (PMID 31601252, 2019). "Among the 20 candidate MCL1-regulating DUBs, USP13 drew our attention because it was amplified in several types of human cancer, particularly in 45.9% of lung squamous cell carcinoma (504 samples) and 28% of ovarian serous adenocarcinoma (603 samples)." (PMID 29335437, 2018).
neutropenia (7 papers, 2011 to 2025). A decrease in the number of neutrophils found in the blood. "In addition to extreme neutropenia, Mcl-1 deficiency resulted in increased macrophage apoptosis and lipid handling, and triggered multinucleated giant cell formation." (PMID 31601924, 2019). "Neutrophils lack several anti-apoptotic Bcl-2 proteins and depend entirely on Mcl-1 expression for survival, as shown by severe neutropenia in Mcl-1 conditional knockout (KO) mice." (PMID 41051248, 2025). "In this study, we evaluated the effects of myeloid Mcl-1 deletion and its accompanying neutropenia on atherosclerosis progression." (PMID 31601924, 2019). "Although neutrophil-specific deletion of Mcl-1 in MRP8-CreMcl1flox/flox (Mcl1ΔPMN) mice also led to severe neutropenia, those mice showed an overt wasting phenotype and strongly reduced survival and breeding, limiting their use as an experimental model of neutrophil deficiency." (PMID 30464050, 2018). "The inclusion of naïve Mcl-1− miceand their Mcl-1+ littermate controls allowed us to distinguishpatterns of cytokine changes elicited by inflammation from those that are solelythe consequence of neutropenia." (PMID 21655273, 2011). "Taken together, these results confirm Mcl-1 as a crucial neutrophil survival factor, also under hyperlipidemic conditions, and demonstrate that Mcl-1 myeloid deletion can be used as a genetic tool to induce a long-lasting, severe neutropenia in atherosclerosis." (PMID 31601924, 2019). "As Mcl-1 is vital for neutrophil survival, whilst presumably having mild effects on macrophage apoptosis, we hypothesized that myeloid Mcl-1 deletion could serve as an efficient neutropenia model during the full pathogenesis of atherosclerosis." (PMID 31601924, 2019). "No signs of neutropenia were observed in mice carrying mutations only in the Lyz2 or Mcl1 gene." (PMID 30464050, 2018). "In addition, the data obtained in our neutrophil viability screen has identified kinase targets whose inhibition significantly impacts neutrophil survival via effects on Mcl-1 and may contribute directly to neutropenia in vivo." (PMID 28938529, 2017). "Indeed, Cre/lox–mediated myeloid-specific deletion of Mcl-1 led to very severe neutropenia without affecting other hematopoietic lineages." (PMID 30464050, 2018).
renal cell carcinoma (7 papers, 2010 to 2024). "Anisomycin in renal cell carcinoma cells can mediate Bcl-2/c-FLIP(L)/Mcl-1/death receptor 4 (DR4) to promote cell apoptosis and exert anti-tumor effects." (PMID 34164339, 2021).
rheumatoid arthritis (7 papers, 2013 to 2024). A chronic, systemic autoimmune disorder characterized by inflammation in the synovial membranes and articular surfaces. "As a member of the pro-survival Bcl-2 subfamily, MCL1 is over-expressed and contributes to suppressing chronic inflammation in rheumatoid arthritis by enhancing the resistance ability of synovial fibroblasts to apoptosis." (PMID 34670585, 2021). "Rheumatoid arthritis fibroblast-like synoviocytes (RA FLSs) obtained from arthritis patients when treated with vorinostat induced apoptosis via generation of ROS and suppressed NF-κB activation and anti-apoptotic proteins (Bcl-xL and Mcl-1)." (PMID 30841513, 2019).
acute leukemia (6 papers, 2013 to 2023). A clonal (malignant) hematopoietic disorder with an acute onset, affecting the bone marrow and the peripheral blood. "Despite these uncertainties, BCL-2 inhibition with venetoclax, and MCL-1 or BCL-XL inhibition potentially, represent a significant advance in targeted treatment approaches to hematologic malignancies and are very promising in acute leukemia and MDS treatment." (PMID 30972300, 2019).
adenoma (6 papers, 2012 to 2022). A neoplasm arising from the epithelium. "It was found that Bcl‐XL instead of Bcl‐2 or Mcl‐1 is required for cell survival and outgrowth during the adenoma‐to‐carcinoma sequence of CRC." (PMID 36254394, 2022). "A tissue microarray (TMA), containing adenoma, adenocarcinoma and normal mucosa specimens was stained for Bcl-xL, Mcl-1 and Bcl-2." (PMID 27537525, 2016). "Surprisingly, Mcl-1 was found to be significantly downregulated in adenomas (P=0.0007) with a slight rebound in the malignant stage (P=0.03)." (PMID 27537525, 2016). "It will also be important to test other proapoptotic agents, for example, Bcl-XL- or Mcl-1–specific inhibitors for their potency for killing adenomas in the presence of sulindac or PP, and whether those drugs might enhance the reduction of colon adenomas by the combined PP/sulindac treatment." (PMID 36860494, 2022). "While intestinal stem cells (ISCs) require BCL-2 for adenoma outgrowth and survival during transformation, ISC-specific MCL1 deletion results in disturbed intestinal homeostasis, eventually contributing to tumorigenesis." (PMID 34117376, 2021). "By targeting antiapoptotic proteins with specific BH3 mimetics in organoid models of CRC progression, we found that BCL-2 is essential only during ISC transformation while MCL1 inhibition did not affect adenoma outgrowth." (PMID 34117376, 2021). "Also in this setting, MCL1 inhibition did not impair adenoma clonogenicity, in agreement with the minimal impact of AZD5991 on APCKO organoids." (PMID 34117376, 2021).
COVID-19 (6 papers, 2021 to 2025). A disease caused by infection with severe acute respiratory syndrome coronavirus 2. "In severe COVID-19 cases, elevated levels of MCL1 indicative of enhanced neutrophil survival, with a higher expression in SevereA compared to SevereD." (PMID 39928675, 2025). "The consistent increase in ICAM1, MCL1, IL1β, and S100A12 expression in neutrophils from severe alive to severe dead patients underscores the critical role of neutrophils in COVID-19 severity." (PMID 39928675, 2025). "Additionally, the donation of functional mitochondria from human MSCshBAK+MCL1 prevented macropore formation in the recipient SARS-CoV-2-infected or NSP4/ORF9b-expressing airway epithelial cells, which can be a potential therapeutic strategy for COVID-19." (PMID 36230930, 2022).
HCMV infection (6 papers, 2014 to 2021). "Akt activated by HCMV infection leads to the upregulation of a unique subset of anti-apoptotic proteins, including myeloid cell leukemia-1 (Mcl-1) protein, heat shock protein 27 (HSP27), and X-linked inhibitor of apoptosis (XIAP), necessary for the survival of infected monocytes." (PMID 34663377, 2021). "HCMV infection of monocytes leads to the up-regulation of Mcl-1 for up to 24 hpi at which point the levels of Mcl-1 begin to slowly decrease until reaching levels of mock-infected monocytes at 72 hpi." (PMID 30274264, 2018). "In contrast to uninfected monocytes, Mcl-1 levels remain stable through the first 24 hours following HCMV infection; after 24 hours, Mcl-1 levels in infected monocytes decline until expression finally reaches the same levels as those observed in mock-infected cells at 72 hours post infection." (PMID 24531335, 2014). "By extending the expression of Mcl-1 in HCMV-infected monocytes when compared to their mock-infected counterparts, HCMV infection allows these cells to navigate the cell viability checkpoint at 48 hours post infection." (PMID 24531335, 2014).
Hypoglycemia (6 papers, 2016 to 2025). A decreased concentration of glucose in the blood. "Western blotting results showed that hypoglycemia and euglycemic conditions induced a decrease in protein expression of cyclin D1 and MCL-1 in both cells." (PMID 26959121, 2016). "Under hypoglycemia/metformin treatment, upregulated Ppp2r5d dephosphorylates GSK-3β, leading to a decline in MCL-1 and cell death." (PMID 39200351, 2024). "Furthermore, when combined with hypoglycemia, metformin binding to tmCLIC1 disrupts the PP2A-GSK3β-MCL-1 pathway, leading to cancer cell death." (PMID 41276810, 2025). "A previous study demonstrated that metformin combined with hypoglycemia impaired tumor metabolic plasticity and growth by modulating the Protein phosphatase 2A (PP2A)-glycogen synthase kinase 3beta (GSK3β)-myeloid cell leukemia 1 (MCL-1) axis." (PMID 39308524, 2024).